NPY (neuropeptide Y)
Diseases named in the same sentence as NPY in open-access papers (continued):
Sharing a sentence is not in itself a finding about the gene and the disease.
Obesity (continued). "In many cases of obesity, the elevated NPY-ergic tone may be due to central resistance to peripheral signals of energy excess such as leptin, which increases with long-term exposure to positive energy balance." (PMID 37452264, 2023). "In general, our study showed that chitosan at 3/g/d for 12 weeks improved all obesity-related cardiometabolic markers (anthropometric indicators of obesity and lipid and glycemic markers) assessed as well as appetite-related hormones (adiponectin, leptin, and NPY)." (PMID 36064382, 2022). "Even though various physiological conditions and pathophysiological processes such as obesity, anxiety, food intake, chronic pain, neurodegenerative disorders, and bone disease have been proven to require NPY to participate, its effect on bone metabolism is still poorly understood." (PMID 35273572, 2022). "Furthermore, NPY signaling is involved in human diseases such as obesity, mood disorders, and cancers." (PMID 35165283, 2022). "Obesity develops when NPY and AgRP levels rise as a result of prolonged or frequent BPA exposure." (PMID 35328389, 2022). "Besides, dorsomedial nucleus NPY knockdown mice showed increased basal and obesity-induced decrease in bone mineral density (BMD) together with reduced activating transcription factor 4 (ATF4) expression level." (PMID 35273572, 2022). "In this context, fat tissue exhibits significant macrophage infiltration, and it appears that activated macrophages may be the actual source of NPY in fat tissue under the conditions of dietary obesity." (PMID 35418942, 2022). "In general, our study showed that chitosan supplementation can improve cardiometabolic parameters (anthropometric indicators of obesity and lipid and glycemic markers) and appetite-related hormones (adiponectin, leptin, and NPY) in adolescents with overweight or obesity." (PMID 36064382, 2022). "Finally, NPY has also been shown to indirectly regulate immune function through pathways that affect obesity, diabetes, mood, and thermoregulation, all of which can then modulate the immune response." (PMID 35448669, 2022). "This may have been due to the increased bodyweight in AgRP‐stimulated mice that could offset the inhibitory effects of AgRP and NPY neuropeptides on GnRH and/or kisspeptin neurons, as prepubertal obesity often advances puberty onset." (PMID 36306199, 2022). "NPY is closely related to obesity and other metabolic diseases." (PMID 34307371, 2021). "Thus, NPY levels in the hypothalamus are an important genetic determinant of an individual’s vulnerability to diet-induced obesity." (PMID 34199898, 2021). "Initial reports of hypothalamic neuroinflammation in obesity postulated that neuroinflammation is caused by stress and dysfunction of the feeding circuitry neurons, anorexigenic POMC, and orexigenic NPY, in the arcuate nucleus (ARC), since inflammation was detected specifically in this region." (PMID 34154608, 2021). "Hence, our findings point toward a novel intracellular mechanism of NPY in the regulation of adipocyte-macrophage crosstalk and highlight NPY antagonism as a promising target for therapeutic approaches against obesity and NAFLD." (PMID 34829968, 2021). "Interestingly, under obesity and insulin resistance, a long-term increase in insulin levels can also lead to an increase in hypothalamic NPY levels, indicating that hypothalamic NPY is resistant to the feedback regulation of insulin elevation." (PMID 34307371, 2021). "Although we examined a comprehensive panel of obesity associated cytokines, there are other inflammatory markers that were not measured in this study, including ghrelin, neuropeptide Y, and the recently emerging advanced glycation end products (AGEs)." (PMID 33764994, 2021). "A study showed that NPY promoted blood vessel formation in abdominal WAT by upregulating Y2R expression on the anterior surface of WAT, increasing the proliferation and differentiation of WAT cells, leading to pathogenic adipose accumulation and obesity." (PMID 34344469, 2021).
Obesity (continued). "Additionally, both central and peripheral sources of NPY can induce obesity by promoting the accumulation of WAT throughout the body." (PMID 34344469, 2021). "Thus, selective over-expression of NPY in the CeA led to increased feeding and decreased energy expenditure, thereby promoting an obesity phenotype, when chronic stress and high fat diet were combined." (PMID 34940594, 2021). "This supports the hypothesis that NPY might be critical in controlling obesity and related diseases." (PMID 34829968, 2021). "Antagonizing NPY receptors and blocking the NPY signaling pathway can attenuate obesity." (PMID 34307371, 2021). "In contrast, NPY contributes to obesity by stimulating food intake and promoting weight gain." (PMID 34381356, 2021). "Furthermore, obesity resistance can be stimulated with a diet that is rich in fat and inhibits the expression of NPY and PPARγ in a rodent model." (PMID 34140894, 2021). "In food-induced obesity, the whole-body energy homeostasis is disrupted, which may be related to abnormalities in hypothalamic neurons, e.g., NPY/agouti gene-related peptidergic neurons stimulating POMC/cocaine- and amphetamine-induced transcriptergic neurons." (PMID 34733235, 2021). "Our study revealed that dietary patterns, in particular, the type of fatty acids used may influence levels of 2-AG, NPY, and omentin, which all are involved in pathways resulting in obesity." (PMID 34466576, 2020). "It is concluded that dietary patterns, in particular type of fatty acids used, may influence the level of endocannabinoids, NPY, and omentin, which all are key regulators of pathways resulting in obesity." (PMID 34466576, 2020). "They reported that HFD feeding decreased hypothalamic AgRP mRNA expression in control mice, but not in mice in which the AT1R was deleted in LepR-containing neurons (the AT1R and LepR are co-expressed in the ArcN), supporting a link between AT1R and NPY suppression with obesity." (PMID 32160920, 2020). "Neuropeptide Y (NPY), a hypothalamic peptide, an essential food intake and/or energy metabolism regulator, is a powerful orexigenic factor hypothalamus, which induces obesity by increasing fat storage and inhibiting the thermogenesis of brown fat tissue." (PMID 34466576, 2020). "Incongruous evidence might be attributed to the co-occurrence of obesity and depression that are opposingly interrelated with NPY and conceivably offset one another." (PMID 33192409, 2020). "Moreover, NPY expression presented sex-dimorphism, boys with obesity showing higher levels than girls with obesity (p = 0.05)." (PMID 33644105, 2020). "However, obesity appears to alter the ongoing activity and responsiveness of arcuate NPY and POMC neurons in a sexually dimorphic way, such that SNA increases in males but not females." (PMID 32160920, 2020). "Finally, it was worth mentioning that NPY exerts biological effects via its receptors and the most well-known being NPY-Y1, NPY-Y2, and NPY-Y5 receptors which are involved in obesity." (PMID 32831640, 2020). "Therefore, NPY has an important relationship with the occurrence and development of obesity and its related complications." (PMID 32831640, 2020). "Several studies also have reported a link between NPY and obesity." (PMID 32831640, 2020). "However, genes associated with obesity have been also described to be associated with HD, such as POMC, NPY, CART, and BDNF." (PMID 32982666, 2020). "Moreover, via the central or peripheral nervous system, NPY is closely connected to body temperature regulation, obesity development, glucose metabolism, and emotional expression, which are all immunomodulatory factors for the immune system." (PMID 33123166, 2020). "Deletion of Mfn1 or Mfn2 in AgRP/NPY neurons prevents fusion and impairs neuronal firing frequency in diet-induced obesity, illustrating that the induction of mitochondrial fusion is required for the paradoxical neuronal activation of AgRP/NPY neurons following exposure to HFD (Figure 2Cii)." (PMID 33240218, 2020).
Obesity (continued). "In regard to NPY sexual dimorphism, lower levels of NPY found in female patients with obesity compared to male patients with obesity may be related to higher levels of leptin, inhibiting NPY production." (PMID 33644105, 2020). "Indeed, simultaneous ablation of arcuate anorexigenic POMC and orexigenic AgRP/NPY neurons results in mild obesity, suggesting a dominance of POMC neurons in such manipulations." (PMID 31557134, 2020). "In this context, neuropeptide Y (NPY), a sympathetic neurotransmitter, might mediate effects on cardiovascular functions, hypertension, obesity, and regulation of inflammatory cells." (PMID 32377539, 2020). "Because obesity is associated with complex changes in the neurophysiology of the POMC and AgRP/NPY neurons, the result of ARC neuromodulation by DBS on the PVN in obese patients is tricky and an optogenetic manipulation may be a preferred approach." (PMID 31057350, 2019). "The appropriate balance of these regulatory peptides may be disrupted if the microbiota composition is altered, as evidenced by germ-free mice having increased levels of pro-obesity peptides like neuropeptide-Y and reduced levels of anti-obesity peptides." (PMID 30678355, 2019). "Obesity is also accompanied by an increased NPY expression in the ARC." (PMID 31423716, 2019). "Indeed, as stress exaggerates diet-induced obesity through neuropeptide Y (NPY)-mediated pathway in visceral WAT38, we observed higher gene expression of NPY receptor (Npy2r) in PWAT of Ob-IF mice, compared to Ob-PF mice (data not shown)." (PMID 30792482, 2019). "Indeed, high‐fat feeding increases hypothalamic NPY expression, with genetic obesity models being characterized by increased NPY mRNA and protein levels." (PMID 31393006, 2019). "Another experiment by Price reported that Nesfatin-1 could inhibit food intake and avoid obesity by inhibiting NPY neurons through calcium signaling pathways." (PMID 31195699, 2019). "This is in agreement with previous reports showing that ghrelin is unable to induce a hyperphagic response in diet-induced obesity and that this effect may be specifically due to ghrelin resistance in NPY/AgRP neurons in the ARC." (PMID 29433631, 2018). "In addition, stress exaggerates diet-induced obesity through neuropeptide Y, leading to the accumulation of abdominal fat." (PMID 29988947, 2018). "Instead with normal NPY and excess calories, an Y2-receptor antagonist induces obesity." (PMID 29674968, 2018). "NPYR in adipocytes appears to play an important role in PTX3- and NPY-induced stimulation of adipogenesis, implying that NPYRs might be a potential therapeutic target for the treatment of obesity." (PMID 30105036, 2018). "As it is clear that BRS‐3 agonist finally exerts anti‐obesity effects, this NPY increase might be a compensatory reaction." (PMID 29568682, 2018). "AgRP and NPY are orexigenic factors inducing hyperphagia and obesity." (PMID 30483218, 2018). "Indeed, a previous study has reported that experimental obesity model exhibited an elevated activity of NPY and its receptors." (PMID 30105036, 2018). "Acute and chronic icv NPY administration result in hyperphagia, obesity and changes in metabolism." (PMID 28373831, 2017). "A relationship was found between obesity and depression; however, NPY polymorphism did not affect depression or obesity." (PMID 29062372, 2017). "Moreover, NPY administration into the PVN stimulates food intake and induces increased PVN neural activity; while sustained, viral-mediated overexpression of NPY within this structure results in obesity." (PMID 28373831, 2017). "The ginsenoside, Rb1, may treat obesity by modifying the serum content and mRNA expressions of neuropeptide Y (NPY), NPY Y2 receptor, and peptide YY (PYY)." (PMID 29234439, 2017). "According to our investigation, to date, no research has been conducted to cover neuropeptide Y gene polymorphisms, obesity and depression in a single study in Iran." (PMID 29062372, 2017).
Obesity (continued). "NPY is involved in some human diseases such as obesity, alcoholism, schizophrenia and depression, each of which might contribute to the development of psychotic behaviors." (PMID 29062372, 2017). "The diet-induced obesity suppressed the neuroendocrine ghrelin system by decreasing ghrelin production in the stomach, as well as by ghrelin resistance in arcuate neuropeptide Y/Agouti-related peptide (NPY/AgRP) neurons." (PMID 28596789, 2017). "Moreover, peripheral NPY has a fundamental role in stress-induced obesity, i.e. NPY is needed to convey the effects of stress on fat storage, adipogenesis and corticosterone secretion." (PMID 27681875, 2016). "Obesity states are characterized by increases in NPY mRNA and NPY release." (PMID 27147943, 2016). "CST significantly decreased the expression levels of genes encoding obesity-promoting neuropeptides (agouti-related peptide, neuropeptide Y), and increased the mRNA levels of obesity-suppressing neuropeptides (proopiomelanocortin, cocaine-and amphetamine-regulated transcript) in the hypothalamus." (PMID 27845741, 2016). "In addition to the increased activity of NPY neurons, Ngn3 mutants display a loss of Pomc expression in the ARC that is associated with postnatal obesity and a loss of leptin sensitivity." (PMID 27533310, 2016). "Furthermore, sustained elevated NPY/AgRP levels perpetuate a dysfunctional feeding circuit resulting in the development of diet-induced obesity (DIO) from overfeeding." (PMID 27893782, 2016). "Furthermore, chronic icv infusion of TTR into OLETF rats lowered DMH NPY levels and ameliorated hyperphagia and obesity." (PMID 27053000, 2016). "Interestingly, NPY knockdown in the hypothalamus increases energy expenditure and its overexpression within the paraventricular nucleus induced obesity via increased food intake." (PMID 26106286, 2015). "Cumulative evidence also suggests that NPY acts as a metabolic signal that may contribute to obesity, hyperinsulinemia, and hyperglycemia." (PMID 25993471, 2015). "The current work aimed at testing the hypothesis that endocannabinoids are also mediating the effects of NPY co-localized with norepinephrine on the development of obesity and MS-like phenotype." (PMID 25915740, 2015). "Interestingly, a short-term NPY overexpression study suggested that NPY influences leptin and insulin secretion independently from food intake and obesity." (PMID 25993471, 2015). "The results suggest that NPY in the periphery and brain noradrenergic neurons may promote obesity and metabolic disease also through modulation of endocannabinoid levels and CB1 receptors." (PMID 25915740, 2015). "Moreover, the relative weight of adipose tissue and Lee index increased in HFD and NPY overexpression groups, which suggested that either HFD or long-term NPY expression in PVN result in obesity." (PMID 25993471, 2015). "Like POMC, NPY signaling may be influenced by ER stress induced by obesogenic diet, and may play a role in the development of obesity." (PMID 26237477, 2014). "Numerous studies demonstrate that NPY is a major mediator in promoting energy storage, positing that it could serve as a potential biomarker for obesity." (PMID 24959194, 2014). "Still, leptin is suggested to exert anti-obesity effects by signaling through “long form” leptin receptors (ObR) abundantly present on both orexigenic neuropeptide Y (NPY)/agouti-related peptide (AgRP) neurons and anorexigenic pro-opiomelanocortin (POMC) neurons in the Arc." (PMID 23554574, 2013). "Given the suppression of CD11c+ ATMs with NPY in lean mice, we examined the possibility that exogenous NPY might blunt inflammation in early obesity in mice." (PMID 23472120, 2013). "NPY was induced by dietary obesity in the stromal vascular cells of visceral fat depots from mice." (PMID 23472120, 2013). "Neuropeptide Y (NPY) is induced in peripheral tissues such as adipose tissue with obesity." (PMID 23472120, 2013).
Obesity (continued). "Given that NPY has a role in immune cell activity and obesity, we investigated the hypothesis that NPY influences the activity of ATMs as a potential link between stress signals, obesity, and inflammation." (PMID 23472120, 2013). "Given the increase in ATM content with obesity and reports of NPY expression in immune cells, we evaluated the hypothesis that ATMs are a source of NPY." (PMID 23472120, 2013). "Given the evidence that NPY can modulate inflammation, we examined the hypothesis that NPY regulates the function of adipose tissue macrophages (ATMs) in response to dietary obesity in mice." (PMID 23472120, 2013). "For example, with obesity, NPY is induced in adipose tissue where it may regulate multiple aspects of adipocyte biology." (PMID 23472120, 2013). "Our results show an early induction of NPY in obese adipose tissue which may dampen the early inflammatory response to obesity." (PMID 23472120, 2013). "However, in a model combining chronic stress and diet-induced obesity, NPY induction in fat correlated with insulin resistance and an increase in ATMs." (PMID 23472120, 2013). "Sexually dimorphic responses to NPY-associated metabolic changes have been reported in NPY Y1 receptor knock-out mice, which develop late-onset obesity without hyperphagia that is more pronounced in female than male mice." (PMID 23118773, 2012). "Moreover, central administration of NPY reduces energy expenditure and chronic infusion of NPY can induce obesity due to overeating." (PMID 23346045, 2012). "Largely secreted NPY stimulates eating and drives overeating-induced obesity." (PMID 22110543, 2012). "Obesity induced by NPY overexpression resulted from diurnal hyperphagia in the three models." (PMID 21799827, 2011). "Studies in humans and animals have shown that administration of CCK, PYY, GLP-1, and NMB could decrease food intake but administration of ghrelin and NPY leads to obesity." (PMID 21390334, 2011). "Invertebrate NPF family neuropeptides are structurally and functionally related to the vertebrate neuropeptide Y (NPY) peptide family, which is involved in the regulation of feeding behavior, stress and obesity, blood pressure, anxiety, memory retention, and circadian rhythms." (PMID 21672256, 2011). "Interestingly, the increase of ARC NPY levels in our model is in accordance to the up-regulation observed in genetic obesity models, such as the Zucker rats (3-fold increase in hypothalamic NPY content)." (PMID 21799827, 2011). "In our study we showed that hypothalamic progenitor cells express feeding-related neuropeptides and differentiate to mature neurons including those described to be affected by hypothalamic neurodegeneration in obesity and Huntington disease: NPY, AGRP, POMC, CART and Orexin-A neurons." (PMID 21589937, 2011). "In our study, the moderately increase on NPY levels in the ARC (3.6-fold as compared to controls) was sufficient to induce obesity, suggesting that a modest long-term increase of orexigenic peptides in the ARC is sufficient to severely alter the energy balance." (PMID 21799827, 2011). "Overall, these findings may be important for the design of therapeutic interventions for obesity that include the NPY." (PMID 21799827, 2011). "Hypothalamic NPY concentrations are elevated before a meal to stimulate appetite, and continuous or repeated central administration of NPY leads readily to obesity, while POMC derived α-melanocyte-stimulating hormone (MSH) counteracts NPY to inhibit feeding and promote negative energy balance." (PMID 19606226, 2009). "Determination of the leptin and NPY concentrations provided evidence that obesity represents disease with neuroendocrine dysfunction and high leptin/NPY ratio, which could be a useful marker for central obesity." (PMID 17721641, 2007). "Leptin and NPY levels showed inverse values in two different obesity types." (PMID 17721641, 2007).